MED10 (mediator complex subunit 10)
Description:
Component of the Mediator complex, a coactivator involved in the regulated transcription of nearly all RNA polymerase II-dependent genes. Mediator functions as a bridge to convey information from gene-specific regulatory proteins to the basal RNA polymerase II transcription machinery. Mediator is recruited to promoters by direct interactions with regulatory proteins and serves as a scaffold for the assembly of a functional preinitiation complex with RNA polymerase II and the general transcription factors.
Synonyms: L6; TRG20; MGC5309; NUT2
Tractability: Small molecule: a structure with a bound ligand is known. PROTAC: ubiquitination databases record sites on it; its protein half-life has been measured.
Gene: Protein-coding gene on chromosome 5 (6,371,874 to 6,378,571, reverse strand). Ensembl gene ENSG00000133398.
Subcellular location: Nucleus
Subcellular location (Human Protein Atlas): Nucleoplasm
Pathways (Reactome):
Gene expression (Transcription): Generic Transcription Pathway; MLL4 and MLL3 complexes regulate expression of PPARG target genes in adipogenesis and hepatic steatosis
Developmental Biology: Transcriptional regulation of white adipocyte differentiation
Disease: RSV-host interactions
Metabolism: PPARA activates gene expression
Gene Ontology:
Molecular function: protein binding; transcription coregulator activity; ubiquitin protein ligase activity
Biological process: positive regulation of transcription elongation by RNA polymerase II; positive regulation of transcription initiation by RNA polymerase II; RNA polymerase II preinitiation complex assembly; protein ubiquitination; regulation of transcription by RNA polymerase II
Cellular component: core mediator complex; nucleoplasm; nucleus; mediator complex; ubiquitin ligase complex
Genetic constraint (gnomAD): Loss-of-function variants: 6 observed, 6.26 expected, observed/expected ratio (o/e) 0.96, 90% interval 0.52 to 1.74. That is too few expected variants to judge how well the gene tolerates losing a copy. Missense variants: 76 observed, 99.13 expected, observed/expected ratio (o/e) 0.77, 90% interval 0.64 to 0.93. Synonymous variants: 41 observed, 39.38 expected, observed/expected ratio (o/e) 1.04, 90% interval 0.81 to 1.35.
Homologues: Orthologues: chimpanzee MED10 (100% identical), dog MED10 (99% identical), macaque MED10 (99% identical), mouse Med10 (99% identical), pig MED10 (99% identical), rat Med10 (99% identical), tropical clawed frog med10 (96% identical), guinea pig MED10 (95% identical), zebrafish med10 (86% identical), rabbit MED10 (50% identical).
Diseases named in the same sentence as MED10 in open-access papers:
MED10 is named in the same sentence as 19 diseases in open-access papers, as found by Europe PMC text mining. Sharing a sentence is not in itself a finding about the gene and the disease. The quoted sentences say what the papers report.
bladder urothelial carcinoma (3 papers, 2021 to 2025). "Research has established an association between aberrant expression of the MED10 gene and advanced tumor stages, as well as diminished survival outcomes in bladder urothelial carcinoma patients." (PMID 40362431, 2025). "Thus, we investigated the role of dysregulated or aberrantly expressed MED10 in the enhanced onco-aggression, disease progression, and recurrence of bladder urothelial carcinoma (UC), as well as the underlying molecular mechanism." (PMID 35096564, 2021).
glioma (2 papers, 2018 to 2021). A benign or malignant brain and spinal cord tumor that arises from glial cells (astrocytes, oligodendrocytes, ependymal cells). "Although MED10 (P = 0.5332) and SOX21 (P = 0.2831) exhibited no differential expression in glioblastoma and normal tissues, they may exhibit differential expression between glioblastoma and low-grade glioma." (PMID 30382873, 2018).
adenoma (1 paper, 2025). A neoplasm arising from the epithelium. "Additionally, COL1A2 (p-value < 0.0001) and MED10 (p-value < 0.05) were significantly higher in the adenocarcinoma group compared to the adenoma group." (PMID 40362431, 2025). "Among the identified molecular targets, ARRB1 was validated using RT-qPCR for adenoma, COL4A5 and RPS3A for CIS, and COL1A2 and MED10 for adenocarcinoma." (PMID 40362431, 2025). "The transcriptional co-regulatory mechanisms pathway was identified, exhibiting DEGs in the adenocarcinoma cohorts compared to adenoma; these genes include CEBPZ, MED10 and PAWR." (PMID 40362431, 2025). "ARRB1 (p = 2.79 × 10−5), CTBP1 (p = 1.33 × 10−5) and CTBP2 genes (p = 0.0002) exhibited notable upregulation in adenoma, whereas COL1A2 (p = 0.0075), CEBPZ (p = 0.0057), MED10 (p = 0.0196) and PAWR genes (p = 0.00215) showed significant upregulation in adenocarcinoma." (PMID 40362431, 2025).
glioblastoma (1 paper, 2018). The most malignant astrocytic tumor (WHO grade IV). "However, MED10 and PTPRN have not been previously reported in glioblastoma-related studies." (PMID 30382873, 2018).
metastatic disease (1 paper, 2021). "Reanalyzing the TCGA BLCA cohort data, we demonstrated that compared to patients without metastasis (M0), MED10 expression is upregulated in metastatic disease (M1)." (PMID 35096564, 2021).
testicular cancer (1 paper, 2016). A primary or metastatic malignant neoplasm that affects the testis. "In testicular cancer only a single overexpression (MED15) was found; while other subunits were underexpressed (MED17, MED7, MED10, MED1)." (PMID 27050271, 2016).
tumor (2 papers, 2021 to 2025). "Furthermore, the survival associations for COL1A2, PAWR and MED10 suggest potential tumor-suppressive roles, supporting their roles in tumor progression as they are upregulated in adenocarcinoma samples in our analysis." (PMID 40362431, 2025). "Using the GPL570 platform [HG-U133_Plus_2], we also demonstrated that increased MED10 expression positively correlated with increased pathological tumor (pT) stage." (PMID 35096564, 2021). "Our bioinformatics-aided gene expression profiling showed that MED10 is aberrantly expressed in patients with BLCA, is associated with high-grade disease, is positively correlated with tumor stage, and confers significant survival disadvantage." (PMID 35096564, 2021). "Also, MED10 transcript expression is positively correlated with increased American Joint Committee on Cancer (AJCC) tumor stage (T1 < T2 < T3 < T4)." (PMID 35096564, 2021). "Interestingly, we demonstrated that MED10 interacts with and is co-expressed with the microRNA, hsa-miR-590, and that CRISPR-mediated knockout of MED10 elicits the downregulation of miR-590 preferentially in metastatic UC cells, compared to their primary tumor peers." (PMID 35096564, 2021). "Our findings highlight the importance of transcriptional co-regulatory mechanisms and ECM remodeling in tumor progression, as well as the potential predictive consequences of ARRB1, COL1A2, MED10, RSP3A and others." (PMID 40362431, 2025).
adenocarcinoma (1 paper, 2025). A common cancer characterized by the presence of malignant glandular cells. "In adenocarcinoma samples, key upregulated candidate biomarkers include COL1A2, CEBPZ, MED10 and PAWR." (PMID 40362431, 2025). "In adenocarcinoma, COL1A2, CEBPZ, MED10 and PAWR were overexpressed, suggesting their involvement in advanced disease progression." (PMID 40362431, 2025).
cancer (1 paper, 2021). A tumor composed of atypical neoplastic, often pleomorphic cells that invade other tissues. "It thus may be inferred that the reduced expression of MED10 (and by inference, pluripotency factors) “cause preferential loss of expression of super-enhancer-associated genes” which are essential for maintaining “cancer cell identity” and promoting oncogene transcription." (PMID 35096564, 2021). "Reaffirming previous data, we demonstrated similarity in the cancer-normal differential expression profile of MED10 (fold change, FC = 1.76, p = 5.7e-06) and hsa-miR-590-5p (FC = 5.78, p = 1.4e-30) in the TCGA BLCA cohort." (PMID 35096564, 2021). "In addition, we showed that high MED10 expression is a non-inferior biomarker of urothelial recurrence compared with markers of cancer stemness; however, MED10 is a better biomarker of local recurrence than any of the stemness markers." (PMID 35096564, 2021).
MED10 also shares sentences with these, for which no sentence is quoted: bladder cancer (1 paper); cell (urothelial) carcinoma (1); Cerebellar hypoplasia (1); eczema (1); hypospadias (1); malnutrition (1); microcephaly (1); renal carcinoma (1); thyroid disorders (1); urothelial carcinoma (1).